MIR548H5 (microRNA 548h-5)
Synonyms: hsa-mir-548h-5
Gene: MicroRNA gene on chromosome 6 (131,792,172 to 131,792,231, forward strand). Ensembl gene ENSG00000266807.
Homologues: Orthologues: chimpanzee MIR548H5 (100% identical). Paralogues in human: MIR548P (80% identical), MIR548AA1 (78% identical), MIR548H3 (77% identical), MIR548K (75% identical), MIR548O2 (75% identical), MIR548S (75% identical), MIR548AQ (73% identical), MIR548AS (73% identical), MIR548AZ (73% identical), MIR548F1 (73% identical), MIR548X (73% identical), MIR548X2 (72% identical), and 13 more.